CDH26 (cadherin 26)
Description:
Cadherins are calcium-dependent cell adhesion proteins. They preferentially interact with themselves in a homophilic manner in connecting cells; cadherins may thus contribute to the sorting of heterogeneous cell types. Ligand for integrins alpha-E/beta-7, ITGAE:ITGAB7, alpha-4/beta-7, ITGA4:ITGAB7 and alpha-4/beta-1, ITGA4:ITGAB1 through which modulates CD4(+) T cells activation.
Synonyms: VR20
Tractability: Antibody: UniProt places it where antibodies can reach, with high confidence; its Gene Ontology location is reachable by antibodies, with high confidence; UniProt predicts a signal peptide or a membrane-spanning region; the Human Protein Atlas places it where antibodies can reach.
Gene: Protein-coding gene on chromosome 20 (59,958,423 to 60,034,011, forward strand). Ensembl gene ENSG00000124215.
Subcellular location: Cell membrane
Subcellular location (Human Protein Atlas): Plasma membrane; Microtubules
Gene Ontology:
Molecular function: alpha-catenin binding; beta-catenin binding; delta-catenin binding; integrin binding; protein binding; cadherin binding; calcium ion binding
Biological process: CD4-positive, alpha-beta T cell activation; adherens junction organization; calcium-dependent cell-cell adhesion; cell migration; cell morphogenesis; cell-cell adhesion mediated by cadherin; cell-cell junction assembly; cell adhesion; cell-cell adhesion; homophilic cell-cell adhesion
Cellular component: plasma membrane; adherens junction; catenin complex; membrane
Genetic constraint (gnomAD): Loss-of-function variants: 73 observed, 85.98 expected, observed/expected ratio (o/e) 0.85, 90% interval 0.7 to 1.03. The upper end of that interval is the gene's LOEUF score, 1.03, which puts it in group 4 of 6, group 1 being the genes least tolerant of losing a copy. Missense variants: 969 observed, 1,042.3 expected, observed/expected ratio (o/e) 0.93, 90% interval 0.88 to 0.98. Synonymous variants: 381 observed, 403.43 expected, observed/expected ratio (o/e) 0.94, 90% interval 0.87 to 1.03.
Homologues: Orthologues: chimpanzee CDH26 (99% identical), macaque CDH26 (88% identical), dog CDH26 (65% identical), rat Cdh26 (61% identical), mouse Cdh26 (60% identical), tropical clawed frog cdh26 (41% identical), zebrafish cdh26.1 (32% identical). Paralogues in human: CDH2 (27% identical), CDH1 (27% identical), CDH4 (26% identical), CDH3 (26% identical), CDH6 (24% identical), CDH20 (24% identical), CDH24 (24% identical), CDH10 (24% identical), CDH22 (24% identical), CDH7 (24% identical), CDH15 (23% identical), CDH18 (23% identical), and 21 more.
Diseases named in the same sentence as CDH26 in open-access papers:
CDH26 is named in the same sentence as 13 diseases in open-access papers, as found by Europe PMC text mining. Sharing a sentence is not in itself a finding about the gene and the disease. The quoted sentences say what the papers report.
myocardial infarction (2 papers, 2022 to 2024). Gross necrosis of the myocardium, as a result of interruption of the blood supply to the area, as in coronary thrombosis. "Moreover, over-expression of CDH26 might be related to myocardial infarction and progression of atherosclerosis, and high salt diet is known as high-risk factor for cardiovascular disease which creates a substrate for arrhythmias, myocardial infarction, and atherosclerosis." (PMID 39358348, 2024). "Overexpression of CDH12 and CDH26 might be related to myocardial infarction and progression of atherosclerosis." (PMID 36539828, 2022).
allergic asthma (1 paper, 2019). A asthma with a basis in a pathological type I hypersensitivity reaction. "Namely, for environment IgE sensitization (METTL1), for allergic asthma (NTRK1), and several for FeNO (MAP3K14, NTRK1, FBXL7, PCSK6, SLC9A3, CDH26, CAPN14, and MAP3K14)." (PMID 31300640, 2019).
allergic disease (1 paper, 2024). An immune response that occurs following re-exposure to an innocuous antigen, and that requires the presence of existing antibodies against that antigen. "Studies have shown that compared with controls, patients with allergic diseases have differentially methylated CpG sites on Cadherin-26 (CDH26)." (PMID 38957776, 2024). "Based on the analysis of existing research data, DNA methylation in allergic diseases, especially the differentially methylated CpG sites in CDH26, may be related to the occurrence of TD, but the relationship between DNA methylation between the two still needs to be further explored." (PMID 38957776, 2024).
asthma (1 paper, 2023). "For example, a previous study showed that abnormality CDH26 gene are characterized by IL-13 stimulation of the airway epithelium and T2 inflammation of the airway epithelium in asthma development." (PMID 37438356, 2023).
eosinophilic esophagitis (1 paper, 2024). Eosinophilic esophagitis (EoE) is a chronic, allergic disease of the esophagus characterized clinically by symptoms of esophageal dysfunction (including vomiting, dysphagia, feeding disorders, food impaction and abdominal pain) which persist after treatment with proton pump inhibitors (PPIs). "The most upregulated gene was CDH26 [log2 (fold change) of 4.50], which is known to be associated with the allergic gastrointestinal diseases eosinophilic gastritis and eosinophilic esophagitis." (PMID 38344408, 2024).
parasite infection (1 paper, 2024). "For instance, PCDH7 is a potential biomarker for host resistance to parasite infection, while CDH26 regulates leukocyte activation and adhesion during allergic reactions." (PMID 38982349, 2024).
infection (2 papers, 2011 to 2016). The state of being infected such as from the introduction of a foreign agent such as serum, vaccine, antigenic substance or organism. "Intriguingly, the transcript abundance of cadherin 26 (CDH26) was significantly induced by infection in both breeds (adjusted P value or FDR < 1.63 × 10−10); and is strongly correlated with worm counts only in CS." (PMID 27197554, 2016). "CDH26 expression was induced to a much greater extent during primary infection than during reinfection, 82 vs. 21 fold, compared to their respective controls." (PMID 21414188, 2011). "Several genes, such as cadherin-like molecule 26 (CDH26), nebulin (NEB), deiodinase, iodothyronine, type II (DIO2), and solute carrier family 38, member 1 (SLC38A1), were significantly up-regulated during both the primary infection and reinfection." (PMID 21414188, 2011).
CDH26 also shares sentences with these, for which no sentence is quoted: breast carcinoma (2 papers); cardiovascular disease (2); allergic rhinitis (1); atherosclerosis (1); head and neck squamous cell carcinoma (1); tumor (1).